EGLN2 (egl-9 family hypoxia inducible factor 2)
Diseases named in the same sentence as EGLN2 in open-access papers (continued):
Sharing a sentence is not in itself a finding about the gene and the disease.
pancreatic endocrine carcinoma (1 paper, 2024). An aggressive, high-grade and poorly differentiated carcinoma with neuroendocrine differentiation that arises from the pancreas. "Moreover, high expression of nuclear forms of EGLN2 and EGLN3 was associated with worse survival in pancreatic endocrine cancer." (PMID 38928200, 2024).
renal clear cell carcinoma (1 paper, 2012). "Finally, level of EglN2, a prolyl hydroxylase, has been shown to be significantly higher in human renal clear cell carcinoma than in normal kidneys." (PMID 22589739, 2012).
renal oncocytoma (1 paper, 2008). "In contrast, in the renal oncocytoma, the functional effects of increased expression of EGLN2 would be to decrease HIFα levels." (PMID 18773095, 2008). "The identification of EGLN2 as a significantly deregulated gene that maps within the paired chromosome region directly implicates defects in the oxygen-sensing network to the biology of renal oncocytoma." (PMID 18773095, 2008). "The identification of EGLN2 as a significantly deregulated gene that maps within the paired chr 19q region directly implicates defects in the oxygen-sensing network to the pathobiology of renal oncocytoma." (PMID 18773095, 2008).
cancer (36 papers, 2009 to 2026). A tumor composed of atypical neoplastic, often pleomorphic cells that invade other tissues. "Several studies have evaluated the association between EGLN2 4-bp insertion/deletion (ins/del) polymorphism (rs10680577) and many cancers." (PMID 32458625, 2020). "The pooled results with six previous published studies support an association between 4-bp ins/del polymorphism of EGLN2 and cancer susceptibility." (PMID 32458625, 2020). "The association between a 4‐bp indel polymorphism (rs10680577) within the distal promoter of EGLN2 and cancer risk has been investigated by several case–control studies in recent years, but investigation results were inconsistent." (PMID 31414584, 2019). "The overall pooled analysis showed that EGLN2 rs10680577 polymorphism was significantly associated with cancer risk under all genetic models." (PMID 31414584, 2019). "The results of our meta‐analysis showed that EGLN2 rs10680577 polymorphism was significantly associated with cancer risk under all genetic models." (PMID 31414584, 2019). "Several studies examined the role of EGLN2 4-bp ins/del polymorphism and the risk of some cancers." (PMID 32458625, 2020). "So we speculated that genetic polymorphisms affecting EGLN2 expression could confer an individual's susceptibility to cancer." (PMID 31414584, 2019). "The present result suggests that EGLN2 rs10680577 polymorphism is associated with cancer risk, and may act as a promising predictive biomarker for cancer risk, especially in Chinese population." (PMID 31414584, 2019). "In conclusion, our meta‐analysis determined that the EGLN2 rs10680577 polymorphism was associated with cancer risk, and may act as a valuable biomarker for predicting cancer risk, especially in Chinese population." (PMID 31414584, 2019). "Among these cancer‐related genes, EGLN2 (OMIM accession number: 606424) has been gaining great attention." (PMID 31414584, 2019). "Although the implication of EGLN2 in many cancers is accepted, mechanisms accounting for its regulation have seldom been discussed." (PMID 29476053, 2018). "Moreover, inactivation of EglN2 down-regulated Cyclin D1 and cell proliferation in several cancer cell lines." (PMID 22589739, 2012). "Thus, the specific roles of EGLN2 varies depending on cancer types and genetic backgrounds." (PMID 29476053, 2018). "The downregulation of EGLN2 and HSPA9 enables cancer cell proliferation even under low oxygen conditions." (PMID 38117844, 2023). "Cytoplasmic P4Hs that hydroxylate HIF-1α, a master transcriptional regulator of cellular responses to hypoxia and well-established mediator of cancer progression, have also been identified (prolyl hydroxylase domain enzymes; PHD1/EGLN2, PHD2/EGLN1, and PHD3/EGLN3)." (PMID 35804902, 2022). "Unlike in other cancer cells, the expression of cyclin D1 in MCL is neither regulated by EGLN2/PHD1 nor by FOXO3A; thus, the molecular mechanism controlling cyclin D1 production and degradation in MCL remains to be elucidated." (PMID 31517438, 2019).
tumor (30 papers, 2009 to 2026). "FBW7 loss induced EglN2 protein stabilization contributes to TNBC tumor progression, which offers a potential novel therapeutic avenue in treating this lethal disease." (PMID 28036276, 2017). "Our analysis revealed a significant increase in overall survival (OS) among patients with high EGLN2 mRNA levels in tumor tissues (p = 0.0052), alongside those with low levels of EGLN3 (p = 0.0272)." (PMID 38928200, 2024). "In a previous study, we demonstrated that EglN2 prolyl hydroxylase contributes to TNBC tumor progression." (PMID 31729379, 2019). "Next, allograft experiments by using EglN2-depleted cell line displayed decreased tumor growth and tumor weight compared to the control cell line." (PMID 28036276, 2017). "In this study, we showed for the first time that EglN2 plays an important role contributing to TNBC tumor growth." (PMID 28036276, 2017). "By using C3Tag transgenic mice and tumor-derived C3Tag cell line, here we report that EglN2 contributes to TNBC tumor progression and genetic knockout of EglN2 improves C3Tag mice survival from tumor progression." (PMID 28036276, 2017). "From this perspective, it may be necessary to deplete EglN2 protein level completely in order to have the durable anti-tumor efficacy in vivo." (PMID 28036276, 2017). "It is worth noting that there appears to be a biphasic tumor development for C3Tag: EglN2−/− mice." (PMID 28036276, 2017). "Our findings suggest that EglN2 may contribute to TNBC tumor growth as a downstream target of FBW7." (PMID 28036276, 2017). "We observed a higher DNA methylation level of the HIF1A promoter region in normal tissues compared to tumors (p = 0.002) and, on the contrary, higher DNA methylation in promoter regions of EGLN2 and EGLN3 (p = 0.04 and p < 0.0001) in HNSCC tumor tissues." (PMID 38928200, 2024). "Consistently, we show here that EglN2 knockdown by shRNA decreases TNBC tumor cell invasion, the phenotype being rescued by WT, but not the catalytically dead mutant, EglN2." (PMID 31729379, 2019). "It will be also interesting to see how EglN2 contributes to TNBC and whether its enzymatic activity may be important for its effect on TNBC tumor progression." (PMID 28036276, 2017).
EGLN2 also shares sentences with these, for which no sentence is quoted: colitis (13 papers); colon cancer (5); pancreatic endocrine tumors (4); paraganglioma (4); Cerebral ischemia (3); chronic kidney disease (3); Hepatic steatosis (3); infection (3); ischemia (3); liver fibrosis (3); renal cell carcinoma (3); anemia (2); breast tumour (2); cervical carcinoma (2); hepatocellular carcinoma (2); hypercholesterolaemia (2); ileitis (2); inflammation (2); Insulin resistance (2); lung disease (2); myocardial infarction (2); rheumatoid arthritis (2); Sepsis (2); ulcerative colitis (2); allergic disease (1); Alzheimer disease (1); autoimmune disease (1); Chronic colitis (1); colonic adenocarcinoma (1); Crohn disease (1).
A further 36 diseases each share a sentence with EGLN2 in 1 paper.